PROK2 (prokineticin 2)
Description:
May function as an output molecule from the suprachiasmatic nucleus (SCN) that transmits behavioral circadian rhythm. May also function locally within the SCN to synchronize output. Potently contracts gastrointestinal (GI) smooth muscle.
Synonyms: PK2; BV8; MIT1; KAL4; HH4
Tractability: Antibody: its Gene Ontology location is reachable by antibodies, with high confidence; UniProt places it where antibodies can reach, with medium confidence; UniProt predicts a signal peptide or a membrane-spanning region.
Gene: Protein-coding gene on chromosome 3 (71,771,655 to 71,785,206, reverse strand). Ensembl gene ENSG00000163421.
Subcellular location: Secreted
Pathways (Reactome):
Signal Transduction: G alpha (q) signalling events; Peptide ligand-binding receptors
Gene Ontology:
Molecular function: protein binding; G protein-coupled receptor binding
Biological process: angiogenesis; chemotaxis; endothelial cell proliferation; negative regulation of apoptotic process; positive regulation of smooth muscle contraction; spermatogenesis; G protein-coupled receptor signaling pathway; inflammatory response; positive regulation of cytosolic calcium ion concentration; sensory perception of pain
Cellular component: extracellular region
Genetic constraint (gnomAD): Loss-of-function variants: 8 observed, 13.73 expected, observed/expected ratio (o/e) 0.58, 90% interval 0.34 to 1.05. The upper end of that interval is the gene's LOEUF score, 1.05, which puts it in group 4 of 6, group 1 being the genes least tolerant of losing a copy. Missense variants: 154 observed, 148.8 expected, observed/expected ratio (o/e) 1.03, 90% interval 0.91 to 1.18. Synonymous variants: 59 observed, 51.1 expected, observed/expected ratio (o/e) 1.15, 90% interval 0.94 to 1.43.
Gene-disease validity (ClinGen):
ClinGen rates the evidence that PROK2 causes each of these diseases.
hypogonadotropic hypogonadism 4 with or without anosmia (semidominant): Definitive.
Homologues: Orthologues: chimpanzee PROK2 (98% identical), macaque PROK2 (95% identical), dog PROK2 (91% identical), pig PROK2 (88% identical), guinea pig PROK2 (84% identical), mouse Prok2 (75% identical), rabbit PROK2 (60% identical), rat Prok2 (56% identical), zebrafish prok2 (46% identical), zebrafish prok1 (42% identical). Paralogues in human: PROK1 (40% identical).
Diseases named in the same sentence as PROK2 in open-access papers:
PROK2 is named in the same sentence as 102 diseases in open-access papers, as found by Europe PMC text mining. Sharing a sentence is not in itself a finding about the gene and the disease. The quoted sentences say what the papers report.
Kallmann syndrome (21 papers, 2007 to 2023). Kallmann syndrome (KS) is a developmental genetic disorder characterized by the association of congenital hypogonadotropic hypogonadism (CHH) due to gonadotropin-releasing hormone (GnRH) deficiency, and anosmia or hyposmia (with hypoplasia or aplasia of the olfactory bulbs). "Two novel variants of the PROK2 gene were found in patients with anosmia, obvious small phallus, and low levels of sex hormones." (PMID 35090434, 2022). "Mutations of PROK2 has also been suggested to be the causative agent for Kallmann syndrome in children." (PMID 33194559, 2020). "To illustrate this point, we describe a frameshift variant in the PROK2 gene, which was differentially classified by two curators in our laboratory—one classified it as likely pathogenic and the other as pathogenic for Kallman syndrome." (PMID 28122645, 2017). "PROK2, a member of the prokineticin family, is positioned on chromosome 3p21.1, and is associated with Kallmann syndrome and hypogonadotropic hypogonadism with normal olfactory function." (PMID 26372733, 2015). "Other recent studies found malformation of the olfactory bulb and gonadotropin-releasing hormone deficiency in PROK2/PROKR2-knockout mice and patients with Kallmann syndrome or hypogonadotropic hypogonadism harboring the PROK2/PROKR2 mutation." (PMID 26317645, 2015). "The phenotypes of Prokr2 and Prok2 knockout mice model aspects of human Kallman syndrome (KS), a partially penetrant genetic disease that causes OB deformity and consequently anosomia and hypogonadism with associated sterility and failure to reach puberty." (PMID 18052978, 2007). "Thus, the PROK2/PROKR2 axis in the OB plays a role in the development and migration/survival of GnRH neurons, and mutations in PROK2 and PROK2 genes lead to a defect in OB neuron migration associated with Kallmann syndrome." (PMID 37895111, 2023). "The occurrence of disease-associated monoallelic mutations may not be rare; for example, this appears to be a common mechanism in Kallmann syndrome caused by mutations in PROKR2 or PROK2 (i.e., an autosomal recessive mode of disease transmission)." (PMID 25077171, 2014). "Loss-of-function mutations in prokineticin 2 (PROK2) and the cognate receptor prokineticin receptor 2 (PROKR2) genes have been implicated in reproductive deficits characteristic of Kallmann Syndrome (KS)." (PMID 36686573, 2022). "In Kallmann syndrome, anosmia/hyposmia is part of the clinical picture, and ANOS1, CHD7, FGFR1, PROK2, PROKR2, and SEMA3A variants were reported to be involved in isolated congenital anosmia." (PMID 32222824, 2021). "Kallmann syndrome caused by ANOS1 gene mutations is inherited by X-linked recessive trait as it is located on chromosome X. FGFR1 and PROK2/PROKR2 lead to autosomal dominantly inherited type of CHH." (PMID 32222824, 2021). "According to these authors’ assessment, mutations in KAL1 appear in about 8% of cases of Kallmann syndrome, FGF8 and FGFR1 both appear in about 10% of cases and mutations both in PROKR2 or PROK2 are responsible for about 9% of cases." (PMID 32722328, 2020). "Furthermore, inactivating mutations of PROK2 and PROKR2 have been discovered in 2–7% of patients with Kallmann syndrome, who suffer from anosmia and hypogonadotropic hypogonadism." (PMID 26313571, 2015). "The role of prokineticin 2 and its receptor in the development of ARDS and other lesions of acute lung injury in sepsis is unknown although anosmia is a prominent feature of SARS Coronavirus-2 infections." (PMID 37638006, 2023).
hypogonadotropic hypogonadism (9 papers, 2015 to 2025). Abnormal ovarian or testicular function due to insufficient hormonal stimulation from the hypothalamic-pituitary axis. "Defects of the PROK2 pathway in humans affect the neuroendocrine control of reproduction by causing hypogonadotropic hypogonadism due to the GnRH deficiency, which is caused by a reduction in the number of GnRH neurons in the preoptic region of the hypothalamus." (PMID 26313571, 2015). "Congenital central hypogonadism is believed to be caused by genetic pathogenic variants, with genes such as ANOS1, FGFR1, FGF8, PROKR2, and PROK2 being implicated." (PMID 39817151, 2025). "Heterozygous variants were detected in PROK2, WDR11 and CHD7 associated with hypogonadotropic hypogonadism, but these variants are insufficient to contribute to the POI phenotype." (PMID 37988663, 2023). "Studies in Prok2 receptor mutant mice and Prok2-/-mice showed olfactory bulb defects and disrupted GnRH neuron migration, resulting in a dramatic decrease in the GnRH neuron population in the hypothalamus as well as hypogonadotropic hypogonadism development." (PMID 30071651, 2018). "Additionally, genetic causes of isolated hypogonadotropic hypogonadism such as KAL1, FGFR1/FGF8, PROKR2/PROK2, CHD7, or GNRH1 gene mutations have not been studied because the patient had a normal puberty and regular menstruation before the amenorrhea." (PMID 26266058, 2015).
colorectal cancer (8 papers, 2015 to 2025). A primary or metastatic malignant neoplasm that affects the colon or rectum. "This is the first report of the association of PROK2 as an angiogenic growth factor in colorectal cancer." (PMID 26317645, 2015). "The inhibition of neutrophil Bv8/PROK2 expression abrogates resistance to anti-VEGF antibodies in genetic models of colorectal cancer." (PMID 40083688, 2025). "Tumor-infiltrating neutrophils in colorectal cancer highly expressed PROK2, which is also involved in promoting angiogenesis." (PMID 38358826, 2024). "PROK2 is show to promote liver metastasis of human colorectal cancer cells in the nude mice tumor xenograft model." (PMID 32887509, 2020). "Using a colorectal cancer cell and mouse model, PROK2 promoted angiogenesis, leading to an increase in colon tumour mass." (PMID 33121134, 2020). "In the cohort studies, high PROK2 expression is found in human colorectal cancer (CRC) tissues and is positively correlated with lymphatic invasion, lymph node metastasis, clinical stage, and postoperative liver recurrence rate." (PMID 32887509, 2020). "Colorectal cancer cells with PROK2 siRNA show a significant decrease in PROK2 expression and tumor growth in mice models." (PMID 32887509, 2020). "After total RNA extraction from 6 colorectal cancer cell lines, we examined the expression of PROK2 mRNA." (PMID 26317645, 2015). "We therefore examined the changes in angiogenesis and tumor growth by suppressing PROK2 expression with Si-RNA in colorectal cancer cell lines having high levels of PROK2 mRNA expression." (PMID 26317645, 2015). "After the colorectal cancer cell lines were transfected with the empty vector or the PROK2 gene vector, these cells were subcutaneously injected into mice." (PMID 26317645, 2015). "In 3 of 6 colorectal cancer cell lines, PROK2 mRNA expression occurred, and the level of expression differed across the 3 lines." (PMID 26317645, 2015). "When PROK2 siRNA was transfected into colorectal cancer cell lines with high PROK2 mRNA expression, angiogenesis and tumor growth in mice were suppressed significantly compared to the cell line with siRNA (control)." (PMID 26317645, 2015). "For investigating angiogenesis and tumor growth in mice, the PROK2 gene was transfected into colorectal cancer cell lines having low PROK2 mRNA expression." (PMID 26317645, 2015). "When the PROK2 gene was transfected into the colorectal cancer cell line with low PROK2 mRNA expression, angiogenesis and tumor growth in mice increased significantly compared to the cell line with the control vector." (PMID 26317645, 2015). "First, the expression of PROK2 in colorectal cancer cell lines was examined, and the expression of PROK2 mRNA was found in many cell lines, suggesting its importance in colorectal cancer." (PMID 26317645, 2015). "We observed that vascularization and tumor growth were promoted in vitro and in vivo after PROK2 was transfected into the colorectal cancer cell lines." (PMID 26317645, 2015). "Si-RNA (control) or Si-RNA(PROK2) was transfected into the colorectal cancer cell lines with high PROK2 mRNA expression and subcutaneously injected in mice to examine tumor mass formation in 3 weeks." (PMID 26317645, 2015). "pcDNA3-GFP-PROK2 vector was transfected into colorectal cancer cell lines having low PROK2 mRNA expression (DLD-1, HCT116, and HT29)." (PMID 26317645, 2015). "In a recent preliminary study, we found PROK2 protein in the serum of advanced colorectal cancer patients." (PMID 26317645, 2015). "We have been establishing anti-PROK2 monoclonal antibody(mAb) to use for clinical trials for advanced colorectal cancer patients." (PMID 26317645, 2015). "In fluid culture of HCT116 colorectal cancer cell line transfected with the PROK2 gene vector, the size of blood vessels significantly increased compared with the cultures of colorectal cancer cell lines with the empty vector." (PMID 26317645, 2015).
colorectal cancer (continued). "PROK2 expression was considered as a potential prognostic biomarker for human colorectal cancer." (PMID 32887509, 2020). "Herein, we examined the role of PROK2 in human colorectal cancer." (PMID 26317645, 2015). "In addition, small interfering RNA (siRNA) was transfected into colorectal cancer cell lines having high PROK2 mRNA expression for investigation of angiogenesis and tumor growth in mice." (PMID 26317645, 2015). "From 6 colorectal cancer cell lines studied, PROK2 mRNA expression was increased in 3 cell lines." (PMID 26317645, 2015). "Angiogenesis and tumor formation were significantly suppressed in vitro and in vivo, indicating that PROK2 may be developed into a new therapy in colorectal cancers with high PROK2 mRNA expression." (PMID 26317645, 2015). "Considering all these findings, the colorectal cancer cell itself may promote PROK2 expression to facilitate the growth and development of cancer." (PMID 26317645, 2015). "Studies have shown that PROK2 might be involved in tumorigenic processes through regulating angiogenesis in glioblastomas and in colorectal cancer, myeloid cell infiltration in pancreatic cancer, growth in hepatocellular carcinoma and tumor progression in prostate cancer." (PMID 32887509, 2020). "PROK2 might be a new angiogenic factor in colorectal cancer." (PMID 26317645, 2015).
Infertility (7 papers, 2009 to 2023). "Our RNA profiling data strongly supported the theory that, in the HIR group of cryptorchid boys, insufficient PROK2 gene expression induces deficient luteinizing hormone secretion, resulting in impaired mini-puberty and infertility." (PMID 30071651, 2018). "Our RNA profiling data strongly support the theory that in the high infertility risk group of cryptorchid boys insufficient PROK2/CHD7/FGFR1/SPRY4 gene expression, together with observed deficient EGR4 and PITX1 signaling, induce deficient LH secretion, which results in impaired mini-puberty." (PMID 29163975, 2017). "Recently, specific phenotypes of PROKR2 and PROK2 knockout mice, have been identified as causative genes for idiopathic hypogonadotropic hypogonadism, a developmental disorder characterized by impaired development of gonadotropin-releasing hormone neurons and infertility." (PMID 33194559, 2020). "PROK2 knockout mice showed impaired male sexual development and infertility, as evidenced by the absence of spermatocytes and spermatids in the seminiferous tubule." (PMID 37275617, 2023). "The complete infertility in genetically modified mice lacking kisspeptin and its cognate receptor GPR54, or lacking prokineticin 2 or prokineticin receptor 2 suggests that some peptidergic systems are of critical importance in hypothalamic control of fertility." (PMID 19390688, 2009).
pancreatic cancer (6 papers, 2013 to 2021). "Use of PROK2 antagonist suppresses the tumorigenic processes through inhibiting angiogenic process in glioma and blocking myeloid cell infiltration in pancreatic cancer." (PMID 32887509, 2020). "Blocking PROK2 with antibodies results in a significant reduction in pancreatic tumor regrowth, angiogenesis, and metastasis in weekly gemcitabine-treated mice." (PMID 32887509, 2020). "Both PROK2 inhibition and metronomic chemotherapy might be used as legitimate ‘add-on’ treatments for preventing post-chemotherapy pancreatic cancer recurrence, progression, and metastasis following weekly gemcitabine therapy in the future." (PMID 32887509, 2020).
Alzheimer disease (5 papers, 2015 to 2023). A progressive, neurodegenerative disease characterized by loss of function and death of nerve cells in several areas of the brain leading to loss of cognitive function such as memory and language. "Aim of the present study was to evaluate the PROK2 and its receptors’ potential involvement in amyloid beta (Aβ) neurotoxicity, a hallmark of Alzheimer’s disease (AD) and various forms of traumatic brain injury (TBI)." (PMID 26477583, 2015). "In Alzheimer’s disease, PROK2 sustains the neuroinflammatory condition and contributes to neurotoxicity, since its expression is strongly upregulated by amyloid-β peptide and reversed by the PKR antagonist PC1." (PMID 31231219, 2019). "This is the first observation describing the direct involvement of the PK system in Alzheimer’s disease, as demonstrated by the significant rise of PROK2 mRNA in the hippocampus of AD patients compared to age-matched, cognitively intact controls." (PMID 31766244, 2019).
diabetes (5 papers, 2016 to 2023). "In this research, we sought to determine the influence of metformin (Met) on diabetes-induced testicular injury and the mechanism involved with a focus on testicular dysfunction, apoptosis, autophagy, and prokineticin 2 (PK2) signalling." (PMID 31871550, 2019). "The PROK2 and PKR2 up-regulation were significantly reduced by a therapeutic 14 day PC1 treatment that started on day 21 after diabetes induction." (PMID 26730729, 2016). "The difference in serum prokineticin-2 levels in patients with and without diabetes was not significant (7.65 ± 3.50 ng/ml, n = 34, vs 6.72 ± 3.09 ng/ml, n = 128, P = 0.131)." (PMID 26728949, 2016).
Sepsis (5 papers, 2020 to 2025). Sepsis is defined as life-threatening organ dysfunction caused by a dysregulated host response to infection. "Moreover, administering recombinant prokineticin 2 to both heterozygous prokineticin 2-deficient mice and wild-type mice prevented sepsis-related mortality and alleviated the multi-organ damage caused by sepsis." (PMID 39201697, 2024). "Although prokineticin 2 has shown promise as a sepsis biomarker in research studies, its incorporation into clinical guidelines or recommendations is still evolving." (PMID 39201697, 2024). "Studies have indicated a significant decrease in prokineticin 2 levels in patients with sepsis and septic shock compared to healthy individuals, with this decrease strongly correlating with sepsis progression." (PMID 39201697, 2024).
Stroke (5 papers, 2018 to 2025). Sudden impairment of blood flow to a part of the brain due to occlusion or rupture of an artery to the brain. "It has been reported that PROK2 mRNA levels increase in vitro, in primary cortical cultures following hypoxia and ROS treatment, and also in an in vivo model of stroke obtained by transient intraluminal middle cerebral artery occlusion." (PMID 33732160, 2021). "On the whole, the authors suggested that PROK2 is an endangering mediator for ischemic brain injury and a compelling target for stroke treatment." (PMID 33732160, 2021). "The PROK2 increase was observed in the ischemic cortex and striatum and was proportionally to the severity of damage, indicating that the stroke-induced PROK2 up-regulation is a consequence of the ischemic damage." (PMID 33732160, 2021). "After stroke, CBM neutrophils preferentially increased the expression levels of Cxcl2, Prok2, Ngp, Thbs1, and Cd177." (PMID 39930981, 2025).
cryptorchidism (4 papers, 2017 to 2022). The failure of one or both testes of a male fetus to descend from the abdomen into the scrotum during the late part of pregnancy. "Molecular observations support a crucial role for PROK2 in the pathophysiology of cryptorchidism, whereby impaired PROK2/CHD7/FGFR1/SPRY4 gene expression controlled by the regulators NHLH2, EGR4, and PITX1 induces LH deficiency." (PMID 35000579, 2022). "Reduced fibroblast growth factor expression may explain the reduction in prokineticin 2 (PROK2) gene expression in samples from boys with cryptorchidism." (PMID 34233607, 2021).
orchitis (4 papers, 2019 to 2022). Inflammation of one or both testes due to viral or bacterial infections. "It has been proven that the pathogenesis of orchitis mainly includes inflammatory cytokine imbalance, oxidative stress, apoptosis, and the PROK2 pathway." (PMID 36289651, 2022). "In summary, the most recent pre-clinical studies related to the varicocele and orchitis models disclosed an overexpression of PROK2, a potential new anti-inflammatory therapeutic target for male infertility." (PMID 36289651, 2022). "We previously found a significant up-regulation of prokineticin 2 (PK2) in the VC animal model, whereas in the orchitis model PK2 promoted IL-1β secretion via the NLRP3 pathway." (PMID 34531872, 2021).